CRP (C-reactive protein)
Diseases named in the same sentence as CRP in open-access papers (continued):
Sharing a sentence is not in itself a finding about the gene and the disease.
psoriasis (continued). "With the improvement in the clinical manifestations of psoriasis, the serum CRP level in the probiotic group decreased more significantly than that in the placebo group." (PMID 39328313, 2024). "Previous studies showed that PASI was significantly associated with increased CRP level, especially in patients with moderate and severe psoriasis, and CRP level decreased with remission of psoriasis." (PMID 39328313, 2024). "Regarding CD4 T cells, a positive correlation with serum CRP was observed only with the percentage of CCR6+ terminally differentiated effector memory cells re-expressing CD45RA (EMRA) in patients with psoriasis." (PMID 37958689, 2023). "In a two-year follow-up of 109 psoriasis patients of Saudi Arabian origin, the presence of enthesitis, synovitis and CRP level was positively correlated with PsA development." (PMID 37298045, 2023). "The baseline values of the NLR, PLR, MLR and CRP in patients with psoriasis before treatment should further be analyzed in a larger cohort of patients in relation to BMI, age, sex, disease duration or nail lesions." (PMID 36769622, 2023). "We also evaluated inflammation markers (CRP, ESR1h, and fibrinogen levels) and detected significantly higher values of these parameters in psoriasis subjects versus controls, in the naive, but also the treated groups." (PMID 38046733, 2023). "In a study involving the administration of B. infantis for the treatment of ulcerative colitis and psoriasis, it was found to lead to a reduction in the C reactive protein (CRP) levels." (PMID 37259345, 2023). "In patients with psoriasis, various biomarkers related to inflammation such as C-reactive protein, erythrocyte sedimentation rate, and platelet activation marker P-selectin are correlated with the severity of psoriasis." (PMID 38179271, 2023). "CRP concentrations were significantly elevated (5.54±4.41 mg/L vs 3.24±0.59 mg/L, p=0.0001) in patients with psoriasis as compared to the control group." (PMID 38046733, 2023). "Compared with the healthy group, circulating leukocyte count, neutrophil count, NLR, ESR, and CRP were higher in the psoriasis group (P < 0.05)." (PMID 37596509, 2023). "The aim of this study is to compare hematological parameters and CRP levels in psoriasis patients with the control group, to evaluate their relationship with PASI score and disease severity." (PMID 37731441, 2023). "CRP levels were lower in individuals with psoriasis who received treatment, however, CRP concentrations remained elevated in psoriasis patients receiving specific therapy versus controls." (PMID 38046733, 2023). "CRP levels have also been reported to be a highly reliable systemic inflammatory marker in patients with Japanese psoriasis." (PMID 37731441, 2023). "Levels of LPB, CRP, and the Firmicutes/Bacteroidetes ratio were higher in the group with psoriasis than in the vegetarian group (p < 0.05)." (PMID 37156688, 2023). "In conclusion, the NLR, MLR, PLR and CRP values significantly reduced after treatment with TNF-α inhibitors in patients with psoriasis." (PMID 36769622, 2023). "After 6–8 weeks of administration, this probiotic strain reduces plasma CRP levels in all three conditions, reduces TNFα in chronic fatigue syndrome and psoriasis, and reduces IL-6 in UC and chronic fatigue syndrome." (PMID 38055306, 2023). "In the case of psoriasis, various studies on systemic inflammation and its circulating markers like high sensitivity C-reactive protein (CRP), tumor necrosis factor-alpha, and interleukin-6 are seen in the picture." (PMID 36106203, 2022). "We collected clinical outcome data such as tender and swollen joint count, enthesitis based on SPARCC score, dactylitis, psoriasis severity, CRP, and BASDAI if axial involvement was present." (PMID 39296732, 2022).
psoriasis (continued). "With regard to the division of the study group into PASI subgroups, patients with severe psoriasis had significantly higher weights, BMI, and CRP levels before and after therapy in comparison to the control group." (PMID 35053087, 2022). "Psoriasis disease severity was evaluated using high sensitivity C-reactive protein (hsCRP), Psoriasis Area Severity Index (PASI) and visual analogue scale (VAS)." (PMID 35163226, 2022). "It is a measure of pro-inflammation of N-glycan side chains connected to the acute phase reactants, which has been shown to enhance the prognostication of the coronary build-up of fat and cholesterol in psoriasis-like CRP." (PMID 36106203, 2022). "Most patients had improvement in multiple clinical domains including tender joint count, swollen joint count, dactylitis, enthesitis, spondylitis, psoriasis, and CRP after 12 weeks of therapy with ixekizumab." (PMID 39296732, 2022). "Inflammatory nature of psoriasis makes higher expression of CRP more evident in serum of psoriatic patients." (PMID 36518145, 2022). "Our results are also in contradiction to what was previously reported in rheumatologic diseases such as RA and psoriasis, where some studies have shown an improvement in activity indices as well as a reduction in CRP." (PMID 35462542, 2022). "The fact that CRP and PON1 activity have a substantial inverse association shows that PON1 activity and inflammation are linked in psoriasis." (PMID 35888704, 2022). "The increased levels of inflammatory markers, such as tumor necrosis factor-α (TNF-α), interleukin-6, and C-reactive protein, have indeed been found in the lung tissue of patients with psoriasis." (PMID 35163689, 2022). "In our study, PTX3 was positively correlated with CRP level which reflects that the protein acts as an indicator of inflammation in psoriasis." (PMID 35888704, 2022). "Patients with PsA had numerically higher CRP than patients with psoriasis only (median[interquartile range] 2.17 [3.31] versus 1.34 [1.74], p = 0.07)." (PMID 36471870, 2022). "Most patients had near-complete resolution of objective measures of disease activity such as SJC, dactylitis, psoriasis, and CRP, but only one patient was able to achieve ≤ 1 TJC, SJC, resolution of enthesitis, dactylitis, and < 3% BSA of psoriasis." (PMID 39296732, 2022). "Psoriasis disease severity was measured using high sensitivity C-reactive protein (hsCRP), Psoriasis Area Severity Index (PASI) and visual analogue scale (VAS)." (PMID 35163226, 2022). "In severe psoriatics, gal-3 positively correlated with BMI and in obese ones with the disease severity index and CRP, which further emphasizes the links with adipose tissue metabolism and promoting inflammation in psoriasis." (PMID 35053087, 2022). "Studies demonstrated that biological therapy decreases blood CRP levels in both psoriasis and coexisting conditions." (PMID 34829740, 2021). "In studies of patients with psoriasis, the supply of these bacteria resulted in a decrease in CRP and the pro-inflammatory cytokine TNFα in the serum of patients." (PMID 33924414, 2021). "Previously, the importance of this relationship in the course of psoriasis was unclear, but now it has been demonstrated that plasma adiponectin decreases and CRP increases as metabolic diseases progress." (PMID 34372872, 2021). "In several studies, a higher level of CRP has been demonstrated in psoriasis as an inflammatory condition." (PMID 31889591, 2020). "Apart from indicating ongoing inflammation, CRP, NLR, and PLR were shown to decrease after treatment with biologic agents for psoriasis, which is linked to the inhibition of systemic inflammation." (PMID 31889591, 2020). "A significant correlation between the relative abundance of Veillonella and inflammatory markers (e.g., h-CRP) was proven, pointing to its role in psoriasis (an autoimmune disease of the skin)." (PMID 32640728, 2020).
psoriasis (continued). "Levels of C-reactive protein (CRP), which is a well-known biomarker of inflammation, have been shown to be elevated in patients with psoriasis, indicating cardiovascular comorbidities." (PMID 31889591, 2020). "Serum NL and PL levels decrease in psoriasis patients after infliximab, adalimumab, and ustekinumab treatment similarly to serum CRP levels." (PMID 32881431, 2020). "The current data support the previous reports indicating that serum CRP level can be used as an appropriate marker for assessing severity of disease in psoriasis." (PMID 32711928, 2020). "High serum CRP levels have been reported in patients with active psoriasis and chronic plaque psoriasis." (PMID 32881431, 2020). "Significant improvements were noted regarding number of swollen and tender joints, enthesitis, extent of psoriasis, C-reactive protein (CRP), pain, fatigue and physical function at six months observation." (PMID 33092646, 2020). "In our study, CRP showed a correlation with I-FABP concentration only in normal weight psoriasis patients." (PMID 31336842, 2019). "Concentration of CRP showed positive correlation with I-FABP only in psoriasis patients with a normal weight (r = 0.71, p < 0.01)." (PMID 31336842, 2019). "The percentage of CCR6+CXCR3− cells within the CD4+ TEM subset in the total cohort of psoriasis and PsA patients significantly correlated with serum concentration of CRP." (PMID 31350460, 2019). "Increased levels of serum C-reactive protein (CRP) have been reported in patients with active psoriasis." (PMID 31275060, 2019). "Complying with this meta-analysis, CRP was significantly higher in psoriasis patients than healthy volunteers and in patients with PASI ≥ 10 than patients with PASI < 10 in the present study." (PMID 29967791, 2018). "The psoriasis patients with PASI > 10 had significantly higher RDW and CRP than healthy controls and psoriasis patients with PASI ≤ 10 (p = 0.001 for all)." (PMID 29967791, 2018). "In many studies, different salivary components have been evaluated in psoriasis patients, such as salivary total protein, salivary immunoglobulin A (IgA), IgG, lysozyme, C-reactive protein (CRP), and Haptoglobin." (PMID 29888276, 2018). "On the other hand, disease duration correlated negatively with serum CRP levels and leukocyte counts in all psoriasis patients." (PMID 29967791, 2018). "The mean ± SD value of CRP in patients with psoriasis was 5.96 ± 9.79 mg/dl, and 19 patients had elevated levels of CRP (CRP >5 mg/dl, according to the local laboratory)." (PMID 30363704, 2018). "There was significantly increased SAF in patients with psoriasis with elevated levels of C-reactive protein (CRP) and increased erythrocyte sedimentation rate (ESR) compared to controls (p < 0.00001; p < 0.00001, respectively, after adjustment to age)." (PMID 30363704, 2018). "A meta-analysis pointed out that CRP levels were elevated in 24 out of 28 studies which were conducted on patients with psoriasis." (PMID 29967791, 2018). "In fact patients with NAFLD/NASH and psoriasis have higher Psoriasis Area Severity Index (PASI) and C-reactive protein than patients with only psoriasis." (PMID 29546055, 2018). "Treatment with fumaric acid esters have been shown to decrease serum CRP level and increase adiponectin level (a cardioprotective adipokine) in patients with psoriasis." (PMID 29065479, 2017). "Other studies demonstrated that treatment of psoriasis patients with etanercept led to decreased CRP levels." (PMID 29065479, 2017). "Psoriasis increased the level of CRP by 117% in the subgroup of patients with MetS and by 125% in the subgroup of patients without MetS (compared to the corresponding controls with MetS and without MetS)." (PMID 29068430, 2017). "CRP mean value in patients with psoriasis was 4.38 ± 6.5 mg/ml and was elevated only in 11 patients, which constitutes 20% of the examined group." (PMID 28932021, 2017).
psoriasis (continued). "Our study supports the independent role of psoriasis and MetS in the increase of CRP and DNA/RNA damage." (PMID 29068430, 2017). "Psoriasis patients have been found to have altered levels of traditional cardiovascular biomarkers, including CRP, soluble CD40 ligand, human matrix Gla protein and fetuin-A." (PMID 29065479, 2017). "An elevated level of CRP can be used as a predictor of inflammation in different diseases, including psoriasis." (PMID 29068430, 2017). "The psoriasis also diminished the relationship between CRP and oxidative damage to nucleic acids existent in controls." (PMID 29068430, 2017). "Correlation analysis does not reflect causality, but it demonstrates a specific regulatory process of the systemic inflammatory reaction (CRP) and oxidative damage to nucleic acids in psoriasis." (PMID 29068430, 2017). "Second, the association between psoriasis and PhA should be verified considering also the disease duration, and the detection of circulating markers of inflammation different from PASI and CRP levels, such as pro-inflammatory cytokines." (PMID 27165166, 2016). "Patients with moderate and heavy psoriasis have significantly higher levels of CRP than the healthy controls." (PMID 28097156, 2016). "The novel finding of this study is the association between the severity of psoriasis, assessed by PASI score and CRP levels, and the degree of adherence to the Mediterranean diet." (PMID 25622660, 2015). "In this context, we evaluated also the relationship between the CRP levels, produced by the liver under the influence of IL-6 as one of the links between the altered cytokine milieu and psoriasis, and the consumption of EVOO." (PMID 25622660, 2015). "When we compared the patients with psoriasis with the controls (before the therapy), we found significantly higher levels of proinflammatory markers (CRP and leptin) and insignificantly lower level of adiponectin." (PMID 26166954, 2015). "Based on the lower limb large joint arthritis, ILBP, psoriasis, radiological sacroilitis, and elevated CRP, he was diagnosed with SpA and psoriatic arthritis, with steroid modified psoriasis, and prescribed NSAIDs and sulfasalazine (SSZ)." (PMID 25431725, 2014). "CRP levels were higher in patients with psoriasis compared with controls (mean CRP 6.68 mg/L vs. 4.97 mg/L; p < 0.001)." (PMID 23965158, 2013). "Both psoriasis and healthy controls had lower C-reactive protein concentrations than did patients with PsA." (PMID 20796300, 2010). "Importantly, we observed a positive, statistically significant correlation between the serum chemerin levels and C-reactive protein, as well as chemerin levels and platelets in the serum of patients affected by psoriasis." (PMID 41788726, 2026). "Additional relevant variables included age, IL-17, TNF, and IFN-γ, while others such as BMI, hs-CRP, TyG index, duration of psoriasis, duration of treatment, HbA1c, smoking, and IL-1β demonstrated negligible or negative importance, indicating limited contribution to model performance." (PMID 41601492, 2026). "Patients with psoriasis exhibit elevated levels of CRP compared to healthy individuals." (PMID 40584532, 2025). "FABP-5 was positively correlated with inflammatory parameters such as CRP and white blood cell counts, which may indicate that it can be used as one of the indicators of inflammation in psoriasis patients." (PMID 40560938, 2025). "OHP and OFP correlated with residual inflammation (CRP) and BMI, waist circumference and markers of metabolic dysregulation associated with visceral obesity in psoriasis patients, but not in controls." (PMID 40917855, 2025). "Pearson correlation analysis between SF and psoriasis severity score, disease duration, and CRP." (PMID 41204483, 2025).
psoriasis (continued). "This is in contrast to the conclusion of a review on the topic of CRP and psoriasis, which inferred CRP to be interchangeable with PASI as a measure of disease severity in patients without psoriatic arthritis, and stresses the necessity for further inflammatory markers." (PMID 38127137, 2024). "The common pathogenesis of cataract and psoriasis may be related to interleukin-6, C-reactive protein, intracellular adhesion molecule- 1, oxidative stress and so on." (PMID 38585265, 2024). "The level of neutrophils was the highest in patients with mild psoriasis (56.9 ± 2.19 and 3.8 ± 0.41, p < 0.05), whereas the CRP concentration was elevated in patients with the moderate/severe course of the disease, but the values of both variables were within normal ranges." (PMID 39409000, 2024). "CRP levels have been shown to decrease after NB-UVB in patients with psoriasis." (PMID 39201319, 2024). "Even more importantly, psoriasis severity (assessed by PASI score and C-reactive protein (CRP)) was negatively associated with the intake of extra-virgin olive oil, fruits, nuts, fish or seafood, vegetables, and legumes, and it was positively correlated with red meat intake." (PMID 38473723, 2024). "The association of NLRP3 (rs10754558) gene polymorphism, TNFα and CRP with disease severity and their role as biomarkers for response to different systemic therapy in psoriasis have not been explored to date." (PMID 38965465, 2024). "CRP, an acute-phase protein produced by the liver in response to inflammation, serves as a sensitive marker of systemic inflammation and has been extensively researched in the context of psoriasis." (PMID 39202262, 2024). "Lastly, MAFLD could affect psoriasis severity through the release of inflammatory mediators from the hepatocyte, namely, reactive oxygen species, C-reactive protein and IL-6." (PMID 36836776, 2023). "Our results show that hematological parameters may be useful in the early diagnosis of psoriasis and that CRP, WBC, NLR, and MLR can be used as biomarkers positively associated with systemic inflammation in predicting disease severity." (PMID 37731441, 2023). "The findings revealed that neutrophil, monocyte, and platelet count, neutrophil/lymphocyte ratio, monocyte/lymphocyte ratio, systemic inflammation response index, systemic immune/inflammation index (SII), and CRP were positively correlated with Psoriasis Area and Severity Index scores." (PMID 37109382, 2023). "In addition, in patients with psoriasis, hsCRP (highly sensitive CRP), OPG (osteoprotegerin), and the CPII: C2C ratio (C-propeptide of Type II collagen: collagen fragment neoepitopes Col2-3/4 ratio) were also found to be independently associated with PsA." (PMID 37298045, 2023). "It has also been suggested that MAFLD could influence psoriasis severity by releasing inflammatory mediators from hepatocytes, including reactive oxygen species, C-reactive protein and interleukin-6." (PMID 37898739, 2023). "Therefore, it has been stated that CRP can be used as a systemic inflammation marker in the evaluation of disease severity in psoriasis." (PMID 37731441, 2023). "Moreover, psoriasis is associated with increased inflammation levels, as revealed by the changes in the complete blood count, NLR, fibrinogen, CRP, and ESR1h discovered in our assessment." (PMID 38046733, 2023). "In all patients, the percentage reductions of the PLR and CRP were positively correlated with that of the PASI at week 52, indicating that the PLR and CRP might act as biomarkers reflecting treatment response to TNF-α inhibitors in psoriasis." (PMID 36769622, 2023). "Finally, we dosed C-reactive protein (CRP), erythrocyte sedimentation rate (ESR), and 25(OH)-vitamin D levels in patients with isolated psoriasis to compare them with patients with psoriasis and skin cancers and to investigate their associations with NGAL." (PMID 36293148, 2022).